MYCN (MYCN proto-oncogene, bHLH transcription factor)
Diseases named in the same sentence as MYCN in open-access papers (continued):
Sharing a sentence is not in itself a finding about the gene and the disease.
neuroblastoma (continued). "Amplifications of MYCN or MYC occur, respectively, in the childhood cancers, neuroblastoma, and medulloblastoma, and the resulting protein overexpression is associated with aggressive growth and poor clinical outcome." (PMID 39079981, 2024). "Cell-line analyses show MYCN-dependent growth inhibition and apoptosis, with approximately 200-fold greater sensitivity of MNA neuroblastoma lines." (PMID 39313128, 2024). "We found that MYCN up-regulated the expression of the core spliceosomal protein, SNRPD3, in models of neuroblastoma initiation and progression." (PMID 38049564, 2024). "We previously demonstrated that MYCN and PRMT5 proteins interact and PRMT5 knockdown led to apoptosis of MYCN-amplified (MNA) neuroblastoma." (PMID 39313128, 2024). "To this end, we observed that, in SK-N-BE-2-C (BE2C) and IMR32 neuroblastoma cell lines, treatment with the 26 S proteasome inhibitor MG132 led to a marked increase in endogenous MYCN protein abundance." (PMID 37543638, 2023). "For additional confirmation, we treated two MYCN-amplified neuroblastoma cell lines, IMR-5 and LS, with the BET bromodomain inhibitor JQ1 in order to inhibit MYCN." (PMID 37402719, 2023). "In neuroblastoma patients, the m5C reader ALYREF forms a nuclear coactivator complex with MYCN to stimulate USP3 transcription, which promotes the tumorigenesis of neuroblastoma." (PMID 37325635, 2023). "In neuroblastoma cells, CLU expression is repressed by the TF MYCN through the recruitment of HDACs and Polycomb group proteins." (PMID 37685987, 2023). "Irrespectively, R26IGF2BP1/MYCN and R26IGF2BP1/IGF2BP1 neuroblastoma show strikingly similar gene expression, most prominently induction of E2F/DREAM-controlled CC genes." (PMID 37246217, 2023). "We propose an essential regulatory role for ADAMTS9-AS2 in neuroblastoma, influencing LIN28B/let-7/MYCN axis signaling." (PMID 37991019, 2023). "Strikingly, however, tumor incidence increased to 100% (8/8) and median survival was reduced to 107 d in R26IGF2BP1/MYCN mice, validating a strong synergy of IGF2BP1 and MYCN in promoting neuroblastoma." (PMID 37246217, 2023). "ASCL1 cis-regulatory elements are targeted by MYCN and additional TF members of the adrenergic (ADRN) neuroblastoma core regulatory circuitry (CRC)." (PMID 37835497, 2023). "In sharp contrast, rather adrenergic neuroblastoma was observed in both, R26IGF2BP1 (TI) and R26IGF2BP1/MYCN (TIM) tumors." (PMID 37246217, 2023). "And they proposed that MYCN plays a significant role as a novel effector of PI3K-mediated regulation of VEGF and hence tumor angiogenesis, in a highly vascularized, malignant neuroblastoma." (PMID 37274289, 2023). "We then constructed a nomogram model based on age of diagnosis, MYCN amplification and ZNF436 to predict the overall survival of neuroblastoma in E-MTAB-1781, TARGET, GSE16476 and GSE62564 datasets." (PMID 37904225, 2023). "Irrespective of certain concerns about off-target effects, there was a relationship between the cytotoxicity of 191Pt-MYCN-PIP and the copy number of the MYCN gene in neuroblastoma cell lines." (PMID 38004392, 2023). "Interestingly, this association is independent of the neuroblastoma tumor stage, maybe indicating a direct connection with MYCN oncogene pathway." (PMID 36675105, 2023). "The Th-MYCN transgenic mouse, the most widely reported transgenic model of neuroblastoma, recapitulates many features of clinical NB progression and has been an important tool for the investigation of NB biology." (PMID 37569447, 2023). "MYCN/IGF2BP1 feedback regulation also stimulates LIN28B expression, a strong inducer of neuroblastoma." (PMID 37246217, 2023).
neuroblastoma (continued). "The WS6 analogues inhibited neuroblastoma cell phenotype in vitro, in part through effects on apoptosis, while their anti-cancer effects required both PA2G4 and MYCN expression." (PMID 36980710, 2023). "(b) Furthermore, our results show that in neuroblastoma cell lines that carry (COG-N-415, LA-N-5, and NB-1643) genomic amplifications of MYCN, robust binding of the TF is mapped across an extended (≥10 kb) genomic region." (PMID 37835497, 2023). "191Pt-MYCN-PIP was synthesized, and its in vitro properties were evaluated in MYCN-amplified and -unamplified neuroblastoma models." (PMID 38004392, 2023). "It should be emphasized that MYCN, a member of the MYC proto-oncogene family, is overexpressed in many types of cancer, including neuroblastoma, and is responsible for promoting proliferation and the survival of tumor cells." (PMID 38067269, 2023). "Eventually, several laboratory studies showed a direct and statistically significant relationship between ornithine decarboxylase (ODC1) and MYCN gene expression, which led to the exploration of newer avenues for the use of DFMO - especially in neuroblastoma." (PMID 37206500, 2023). "This study showed that MYCN was highly expressed in the serum of neuroblastoma in children, suggesting that its overexpression may play an important role in activating the vitality of neuroblastoma tumor cells and may promote the growth, migration, and invasion ability of tumor cells." (PMID 37592273, 2023). "In a large tumor cohort of neuroblastoma, tumors with high mitotic gene expression were identified as being highly aggressive with expression of MYC target genes, likely stemming from MYCN amplification or high cMYC activity." (PMID 37958555, 2023). "In neuroblastoma, ASCL1 appears to be under direct regulation by the LMO1 and MYCN oncogenes, and its overexpression correlates with poorer survival of patients with tumors." (PMID 37958729, 2023). "The endogenous expressions of METTL3 and ALKBH5 of the neuroblastoma cell lines regulated the m6A modification in ADAMTS9-AS2, thus affecting its RNA stability and its downstream MYCN expression." (PMID 37991019, 2023). "The purpose of this study is to characterise and evaluate our novel WS6 analogous as inhibitors of MYCN and PA2G4 oncogenic functions in neuroblastoma." (PMID 36980710, 2023). "A previous study revealed that MYCN upregulates EZH2, leading to the inactivation of a tumor suppressor program in neuroblastoma; meanwhile ATRX in-frame fusion neuroblastoma is sensitive to EZH2 inhibition." (PMID 36675163, 2023). "A small molecule known to bind PA2G4, WS6, significantly decreased tumorigenicity in TH-MYCN neuroblastoma mice, along with the inhibition of PA2G4 and MYCN interactions." (PMID 36980710, 2023). "Based on a study using neuroblastoma-derived cell lines, even the transactivation deficient mutant form of RUNX3 promotes ubiquitination and protein degradation of MYCN, suggesting that RUNX3 might recruit an E3 ubiquitin ligase of MYCN in a transactivation-independent manner." (PMID 36831211, 2023). "Another BET inhibitor, OTX015, is effective against mouse and human MYCN-driven neuroblastoma in models, as it can selectively disrupt the binding of BRD4 and SEs and lead to the repression of MYCN expression." (PMID 36720920, 2023). "The studied cohort included 38 patients aged <12 months; 34 of them had a normal MYCN status and all were treated in accordance with the therapeutic guidelines of an ad hoc SIOPEN (International Society of Paediatric Oncology Europe Neuroblastoma) protocol." (PMID 36831529, 2023). "On the contrary, neuroblastoma patients with ZNF436 low expressions and with MYCN amplification had significantly shorter overall survival in E-MTAB-1781 and TARGET datasets." (PMID 37904225, 2023).
neuroblastoma (continued). "Neuroblastoma (NB) is a genetically heterogeneous tumor characterized by pleomorphic cells, including those with MYCN amplification that are highly glycolytic, presenting the opportunity to use glycolytic inhibitor 2-deoxyglucose (2DG) to suppress NB cell growth." (PMID 36675163, 2023). "MYCN-amplification in neuroblastoma elevates fatty acid uptake, exposing a metabolic vulnerability that can be exploited by targeting FATP2, a fatty acid transport protein regulated by MYCN whose inhibition supresses tumour growth in vivo." (PMID 37414143, 2023). "Numerous tumor-associated genes and antigens, including the MYCN proto-oncogene (MYCN) and disialoganglioside (GD2) surface antigen, have been found by the molecular analysis of neuroblastoma cells." (PMID 37239815, 2023). "Based on MYCN amplification and ZNF436 expression level, neuroblastoma patients were classified into different sub-groups." (PMID 37904225, 2023). "MYCN is a transcription factor of the MYC family, which consists of three paralogues: cellular (c-), lung-carcinoma derived (l-), and neuroblastoma-derived (n-)–myelocytomatosis (myc)." (PMID 38001143, 2023). "The heat map shows the clustering in relation to age, International Neuroblastoma Staging System (INSS) stages and MYCN status, along with the expression of the genes used for clustering in 1811 patients." (PMID 37479876, 2023). "MYCN is a versatile transcriptional driver of oncogene expression, most prominently in MNA neuroblastoma." (PMID 37246217, 2023). "WS6 analogues also inhibited the malignant neuroblastoma cell phenotype in vitro; their cytotoxicity was partially dependent on PA2G4 and MYCN protein expression." (PMID 36980710, 2023). "In neuroblastoma, our analysis identified the transcription factors ISL1, HAND2, PHOX2B, PHOX2A, and MYCN as the top five targets critical for the survival of cell lines." (PMID 37297004, 2023). "MYCN amplification was first identified in neuroblastoma (NB) cell lines and tumor specimens." (PMID 37046804, 2023). "By disrupting the PA2G4-MYCN interaction, treatment with WS6 increased MYCN degradation, in turn decreasing overall levels of MYCN and PA2G4 protein in neuroblastoma cells." (PMID 36980710, 2023). "ALYREF and MYCN form a transcriptional activator complex, which upregulates USP3 expression, promoting the growth and tumorigenicity of MYCN-amplified neuroblastoma cells." (PMID 37537569, 2023). "Consistently, several patients categorized in the high-MYCN mRNA expression group who survived neuroblastoma concomitantly possessed high mRNA expressions of RUNX3, suggesting that RUNX3 has an ability to overcome the aggressive behavior of MYCN." (PMID 36831211, 2023). "IGF2BP1 is a post-transcriptional enhancer of oncogene expression, including MYCN and BIRC5, in various cancers with exceeding expression in Chr 17q unbalanced neuroblastoma." (PMID 37246217, 2023). "This suggested effective targeting of MYCN/IGF2BP1 by combined BRDi and IGF2BP1i in MNA neuroblastoma." (PMID 37246217, 2023). "In neuroblastoma, literature evidence paint a picture where AHCY is constitutively active in cancer cells, but further enhanced by MYCN." (PMID 36870971, 2023). "In fact, MYCN-amplification has been shown to promote both glycolysis and OXPHOS in neuroblastoma, and its inhibition triggers a mitochondrial respiratory chain defect and accumulation of lipid droplets, signifying a reduction in fatty acid oxidation." (PMID 37414143, 2023). "The majority of patients (n = 33, 89.2%) had INSS stage 4 (M) neuroblastoma at diagnosis, and four (10.8%) had INSS stage 3 (L2) disease with MYCN amplification." (PMID 37629294, 2023). "The expression of MYCN, AURKA, TGFBR1, and TGFBR2 is directly inhibited by miR-186, which can inhibit the tumorigenetic potential of neuroblastoma." (PMID 37426487, 2023).
neuroblastoma (continued). "In neuroblastoma, IGF2BP1 synergizes with MYCN by transcriptional/post-transcriptional feedforward regulation, which unleashes an oncogene storm and genomic instability reminiscent of high-risk diseases." (PMID 37246217, 2023). "Neuronal MYC (MYCN), a member of the MYC family, has been identified as a CLU negative regulator in human neuroblastoma cells." (PMID 37685987, 2023). "We have previously demonstrated that BGA002, as a single agent, was able to specifically inhibit MYCN expression in neuroblastoma cell lines; furthermore, in combination with 13-cis RA, BGA002 has shown an improvement in MYCN transcriptional inhibition." (PMID 36765949, 2023). "In this context, we have previously shown that a novel strategy using an MYCN-specific antigene peptide nucleic acid (agPNA) oligonucleotide (called BGA002) is effectively able to silence MYCN expression by acting directly at the DNA level in neuroblastoma (NB)." (PMID 36765949, 2023). "To confirm the dependency of CCDC86 expression on MYCN, we then used the neuroblastoma cell line TET21-N, in which MYCN expression can be modulated by doxycycline." (PMID 36695333, 2023). "The rationale is that MYCN upregulates EZH2, leading to the inactivation of a tumor suppressor program in neuroblastoma, while ATRX in-frame fusion neuroblastoma is sensitive to EZH2 inhibition." (PMID 36675163, 2023). "Our results show that G9a/Ehmt2 and GLP/Ehmt1 expression is higher in tumors with poorer prognosis, including St4 International Neuroblastoma Staging System (INSS) stage, MYCN amplified NB, and metastatic ES." (PMID 37894922, 2023). "MYCN stability detected by the joint of IHC and FISH is a good choice to predict the prognosis of neuroblastoma." (PMID 35820898, 2022). "In neuroblastoma cells, P2X7R activation induces PI3K/Akt/GSK-3β/MYCN activation as well as HIF-1α/VEGF pathways." (PMID 35267424, 2022). "For neuroblastoma the information is a little more limited than for PPGL, but from increases in methoxytyramine can be used to assess likelihood of MYCN amplification, which has prognostic significance." (PMID 35957826, 2022). "CDK2 inhibition suppressed the progression of MYCN-amplified neuroblastoma, and CDK2 antagonists represent potential therapeutic drugs in MYCN-driven neuroblastoma." (PMID 35655142, 2022). "Overall, age at diagnosis, MYCN amplification, CCNE1 and SESN1 were independent prognostic factors in at least four independent paediatric neuroblastoma cohorts." (PMID 35655142, 2022). "In primary neuroblastomas, differences in CBS expression correlated with histone modifications and methylation of intragenic CpGs dependent on genomic MYCN status." (PMID 35484422, 2022). "MYCN directly interacts with LSD1 and inhibition of both MYCN and LSD1 was shown to be an efficient strategy for inhibition of neuroblastoma cell proliferation." (PMID 34522028, 2022). "It was recently demonstrated that in MYCN-amplified neuroblastoma cell lines, retinoic acid induces reprogramming of the ADRN CRC, leading to massive downregulation of MYCN expression, tumour suppression, and cell differentiation." (PMID 36147741, 2022). "Two additional human paralogs were eventually identified: MYCN (N-Myc) and MYCL (L-Myc) that can be found in neuroblastoma and lung cancer samples, respectively." (PMID 35267559, 2022). "N-MYC proto-oncogene protein (MYCN) and Anaplastic Lymphoma Kinase (ALK) are the two important oncogenic drivers of neuroblastoma." (PMID 36585695, 2022). "First, we verified that miR-34 was tumor suppressive in neuroblastoma cells by transfecting the three individual miR-34s into BE2C cells, a commonly used neuroblastoma cell line with MYCN amplification." (PMID 36612203, 2022). "Considering the importance of MYCN and ALK during neuroblastoma tumorigenesis, cell lines with specific genetic alterations of MYCN and ALK have been included." (PMID 36585695, 2022).
neuroblastoma (continued). "In neuroblastoma, the expression level of AHCY was increased in MYCN-magnified cancer specimens and neuroblastoma lineage cells." (PMID 36211359, 2022). "A report has shown that the expression of GLDC is significantly increased in MYCN amplified neuroblastoma tumors and cell lines, and GLDC plays a key role in maintaining the proliferation of neuroblastoma cells." (PMID 36275705, 2022). "Tumors overexpressing MYC-family protein (MYCN overexpression detected in ~20% and MYC overexpression detected in ~10% of neuroblastomas of the undifferentiated and poorly differentiated subtypes) are collectively named MYC-driven neuroblastomas." (PMID 35053227, 2022). "MYCN, ATF4, and KDM4C all contribute to transcriptional upregulation of GOT1, GOT2, GPT, GPT2, and PSAT1 in neuroblastoma cells." (PMID 36077650, 2022). "Both MYCN and hypoxia-inducible factor 1α (HIF-1α) are required for sustaining the aerobic glycolysis phenotype in neuroblastoma cells by transcriptional upregulation of glycolytic enzymes, including hexokinase 2 (HK2) and lactate dehydrogenase A (LDHA)." (PMID 36077650, 2022). "In our comparison between two neuroblastoma cell lines representatives of ALK-driven and MYCN-amplified disease, there is clearly heterogeneity of response to ASCL1 knockout despite similar initial expression levels." (PMID 36263020, 2022). "In neuroblastoma, it has been reported that the 3′UTRs of VEGF and MYCN, a homologue of c-Myc, contain AREs that can be bound to, and stabilized by MDM2." (PMID 35326742, 2022). "MYCN, a MYC paralog, is frequently amplified in human neuroblastoma and was amplified in three human GCs in TCGA cohort." (PMID 34387762, 2022). "ODC has been recognized as a potent oncogenic transforming factor, and in neuroblastoma, it is the most well-studied target of the transcription factor c-MYC/MYCN." (PMID 36551330, 2022). "Overexpression of MYCN or the constitutively active mutant of ALK, e.g., ALKF1174L, in neural crest cells can induce neuroblastoma in mice." (PMID 36585695, 2022). "As such, combining PBNP-PTT with MYC targeting via drugs such as I-BET726 or JQ1 in MYCN-amplified neuroblastoma cells may generate immunogenicity more similar to that seen in SH-SY5Y cells, and may provide effective treatment for high-risk neuroblastoma patients with MYCN amplification." (PMID 35326601, 2022). "The ALK gene is situated in proximity to MYCN and ALKAL2 on chromosome 2p and it has been argued that co-amplification of these three explains the inferior outcome in neuroblastoma patients with 2p gain." (PMID 35362827, 2022). "The consequence of HSP90 inhibition on neuroblastoma cells, both IMR-32 and SK-N-AS, was growth suppression and a decrease in MYC or MYCN expression." (PMID 36185250, 2022). "NYCM was found to co-immunoprecipitate with MYCN and kinase GSK3B, which natively phosphorylates MYCN to target it to the proteasome for degradation, in both neuroblastoma and bladder cancer lines." (PMID 35451603, 2022). "Here, we have investigated the role of ASCL1 in maintaining proliferation and controlling differentiation in both MYCN amplified and Anaplastic Lymphoma Kinase (ALK)-driven neuroblastoma cells." (PMID 36263020, 2022). "Reduced binding of these factors is likely to contribute to the reduced proliferation of ASCL1 KO cells, particularly in the case of MYCN/MYC, whose role in driving proliferation in neuroblastoma is very well documented." (PMID 36263020, 2022). "PLAGL2 was recently described as a regulator of MYCN expression in peripheral neuroblastoma, with knockdown of PLAGL2 inducing neurite outgrowth and differentiation in neuroblastoma cells." (PMID 35763016, 2022).